MMP13 (matrix metallopeptidase 13)
Diseases named in the same sentence as MMP13 in open-access papers (continued):
Sharing a sentence is not in itself a finding about the gene and the disease.
tumor (continued). "In human tumors, a high MMP-13 immunostaining index was found in tumor cells from invasive lesions (24/27), but in none of the non-invasive (0/4) (p=0.001)." (PMID 26193700, 2015). "In addition to MMP2 and MMP9, we investigated the expression of MMP3, MMP11, MMP13 and MMP14 in tumour cells." (PMID 26284589, 2015). "Since we observed a decrease in tumor burden with the loss of MMP13 in both normal and steatotic mice, we focused on the role of MMP13 on tumor metastasis to the liver irrespective of the diet." (PMID 25880591, 2015). "NPC tumor samples compared with adjacent normal tissues, whereas the mRNA levels of MMP13 and MMP28 were not significantly different between the tumor and adjacent normal tissues." (PMID 24885469, 2014). "Upregulation of HAS2 and MMP-13, in a similar fashion as TGFBI may imply their collective role in tumor progression." (PMID 25369402, 2014). "This suggests that the small tumor size in MMP-1 and MMP-13 knockdown mice could be due to low cell proliferation." (PMID 25527274, 2014). "In parallel, upon RUNX2 knockdown, we have observed a predominant and strong downregulation of gene nodes known to be implicated in EOC tumorigenesis (PTGS1/COX1, FGF2, IL1A, Sapk, C/ebp, SELE, UBQLN1, PSAT1, ALDH1A1, GDF15, MTHFD2), including EOC tumor invasion/metastasis (MMP1, MMP13, Creb);." (PMID 24124450, 2013). "Therefore, more marker genes like for example MMP13, UBE2Q2, Nectin-4 or ALDH will have to be tested for their ability not only in tumour cell detection but also in tumour cell characterization." (PMID 24202442, 2013). "This difference in metastasis was not due simply to differences in tumor burden between the WT and MMP13 KO animals, as tumor burden was unchanged." (PMID 24010522, 2013). "The proportion of cancer cells expressing MMP13 varied greatly, ranging from no detectable MMP13 in 25% of patient samples, through focal expression, to expression throughout most of the tumor." (PMID 22253746, 2012). "MMP-13 is not expressed by normal epidermal keratinocytes in intact skin or during wound repair, but it is readily expressed by tumor cells in cutaneous SCCs." (PMID 22427941, 2012). "All of the target genes were expressed in the control and tumor samples, with the exception of MMP-13, which was weakly expressed or not amplified in approximately half of the tumor samples (16 of 35 dogs)." (PMID 21726449, 2011). "In accord with the in vitro growth curves, the in vivo growth of MDA-MB-231 was independent of MMP-13 expression since the tumour masses developed from the different clones injected were of similar size." (PMID 22032644, 2011). "In accord with the levels of MMP-13 expression in the tumours transfected with the different shRNAs, the extent of bone erosion was much higher in lesions produced by WT and scrambled MMP-13 cells than that of MMP-13 shRNA clones." (PMID 22032644, 2011). "The absence of MMP13 did not influence tumor growth, vascularization, progression to more advanced tumor stages, or metastasis to the lungs, and the absence of MMP13 was not compensated for by expression of other MMPs or tissue inhibitor of metalloproteinases." (PMID 18698413, 2008). "Since we found no changes in tumor progression in the absence of MMP13, we explored the possibility that the lack of MMP13 activity was compensated for by changes in expression of other MMPs or in their inhibitors, the TIMPs." (PMID 18698413, 2008). "We followed tumor growth in a cohort of littermate MMTV-PyMT;Mmp13+/+ (n = 38) and MMTV-PyMT;Mmp13−/− females (n = 25) by weekly palpations and caliper measurements until 13 weeks of age, when tumors were isolated for histological examination and the lungs isolated to determine metastasis burden." (PMID 18698413, 2008). "Tumor expression of MMP-13 negatively correlated with patients' OS regardless of the Her-2/neu status." (PMID 18373849, 2008).
tumor (continued). "We verified that the absence of MMP13 did not affect the development of the mammary epithelium and therefore would not affect tumor progression indirectly by influencing the number of mammary epithelial cells." (PMID 18698413, 2008). "Tumor-derived, but not stromal fibroblast-derived, MMP-13 correlated with aggressive tumor phenotypes." (PMID 18373849, 2008). "High levels of MMP-13 expression, both in cancer cells and in peritumoral fibroblasts, correlated with lymph node metastases (p < 0.001), but not with tumor size and histological grade." (PMID 18373849, 2008). "In conclusion, we found that the absence of MMP13 in the MMTV-PyMT mice did not result in any differences in tumor progression to invasive and metastatic breast carcinoma." (PMID 18698413, 2008). "Therefore, we investigated the expression of MMP-13 and TIMP1 in biopsy specimens of HNSCCs to determine the relationship between the expression of these proteins and the mode of tumor invasion." (PMID 15291964, 2004). "However, we did fail to identify any statistically significant relationship between the degree of staining for MMP-13 or TIMP-1 and the patient's age, sex, tumor site, or tumor histologic grade." (PMID 15291964, 2004). "Therefore, CEMIP may have a positive correlation with MMP2, MMP7, MMP13, and MMP14 and regulate tumor cell EMT through MMPs to promote tumor cell migration." (PMID 37662915, 2023). "In MMP13 positive cases, MMP13 expression was absent from the cancer cells and primarily localised to β6 positive myoepithelial cells, as well as fibroblast cells in the tumour periphery, with a positive correlation observed between the percentage of MMP13 and β6 positive cells per duct." (PMID 36864079, 2023). "Furthermore, the TCGA and GEO databases demonstrated that MMP‐13 expression is higher in tumour tissues than in adjacent normal tissues." (PMID 37710409, 2023). "In addition, expression of molecules involved in ECM remodeling such as several metalloproteinases (MMP2, MMP9, MMP10 and MMP13), serine protease (PLAU) collagens, fibronectins and integrins indicate that functional EMT transition and metastasis take place within the tumor microenvironment." (PMID 34946170, 2021). "Furthermore, EDW01 displayed MT1-MMP and MMP-13 at the tumour-stromal boundary, but did not express these factors or MMP-2 and MMP-9 within the tumour mass itself." (PMID 33276802, 2020). "Moreover, a marked reduction in vascular endothelial growth factor (VEGF) expression, CD31+ blood vessels, CD4+ Foxp3+ Treg cells and the expression of MMP-2, MMP-9, MMP-13 and C-X-C motif chemokine receptor 4 (CXCR4) in the tumour stroma were observed in the Smad3−/− tumour microenvironment." (PMID 28262747, 2017). "MMP‐13 cleaves the Ln‐5 fragments Ln‐5γ2ʹ and Ln‐5γ2x into smaller fragments, which prevents the transfer of the EGFR molecular signal into the cell, preventing the signal from inducing the rearrangement of the actin cytoskeleton and affecting the vascular phenotype of aggressive tumour cells." (PMID 28766880, 2017). "Further, levels of related MMPs including MMP1, MMP8, MMP14, MMP2 and MMP9 which have previously been shown to affect tumor cell invasion were not evaluated in these studies and could compensate for MMP13 levels." (PMID 25880591, 2015). "As VM patterns are composed of laminin, which co-localizes with PAS-positive networks, we propose that MMP-13 degrades the PAS-positive and laminin-positive substances, which constitute the basement membranes of VM; their destruction could thus expose tumor cells more directly to blood flow." (PMID 25749207, 2015). "Although we did not observe changes in collagen in the liver, MMP13 may mediate release or activation of critical factors involved in tumor cell extravasation." (PMID 25880591, 2015). "Hence, there is no consensus and it seems likely that a fine tune in MMP13 tumour content is involved in regulating nodal metastasis." (PMID 24229053, 2013).
tumor (continued). "Together these results suggest that stromal host MMP13 depletion alters both collagen I macrostructural (i.e. fiber arrangement, ordering, and orientation), and molecular (fibril) microstructural properties (as quantified by collagen I normalized BSHG and FSHG/BSHG) at the tumor periphery." (PMID 24010522, 2013). "Some of these gene nodes have been shown to be functionally involved in other cancer types, including regulation of tumor cell proliferation (Creb, C/ebp, ATF3, ATF4), invasion (MTHFD2, FGF2) and metastasis (PTGS1/COX1, E-selectin, ATF3, FGF2, IL1A, MMP1, MMP13)." (PMID 24124450, 2013). "However, our measurements of vascular diameter, length and volumes in MMTV-PyMT tumors did not reveal any effect of MMP13 on tumor vascularization." (PMID 18698413, 2008). "Furthermore, the correlation between MMP-13 expression and clinical parameters, including tumor size, histological grade, regional lymph node involvement, presence or absence of distance metastasis and tumor biomarkers was also assessed in this study." (PMID 34452576, 2021). "Interestingly, MMP13 inhibition disturbs the positive effect of ETV4 on MMT proliferation, migration, and invasion, and we demonstrate that MMP13 acts as a relay of ETV4 in its functional role in the mammary epithelial tumorigenic cells in vitro as well as in tumor graft assays in vivo." (PMID 29996935, 2018). "In addition, AJUBA mRNA levels were significantly associated with elevated MMP10 and MMP13 expression in 179 ESCC tumor tissues (r = 0.441, P < 0.001 and r = 0.404, P < 0.001, respectively), suggesting that AJUBA promotes the expression of MMP10 and MMP13 in ESCC." (PMID 27172796, 2016). "These MMP13+ cell bodies found around the tumor periphery in WT but not MMP13 KO mice suggest the presence of peritumor (and possibly infiltrating) MMP13+ stromal cells which may contribute to the altered TACS patterns and metastases observed in WT versus MMP13 KO mice." (PMID 24010522, 2013). "The results showed that tumor cells from nonmetastatic tumors expressed high levels of MMP1, KRT1, and MMP13 and low levels of MGST1, FAM133A, and FMO3." (PMID 36569924, 2022). "MMP7, MMP13, and MMP10 were significantly upregulated, while MMP12 and MMP9 were downregulated in metastatic tumour samples compared with nonmetastatic tumour samples." (PMID 31996191, 2020). "Though OPN was not essential for tumor formation, it was indicated that OPN is involved in early stage intestinal tumorigenesis in part by upregulation of MMP-3, MMP-9, and MMP-13, and infiltration of macrophages and neutrophils." (PMID 28505114, 2017). "At day 24, considerable tumor growth was observed in controls, while almost no tumor growth was observed in MMP-1 and MMP-13 knockdown mice (data not shown)." (PMID 25527274, 2014). "MMP-13 can also deactivate non-matrix proteins, such as MCP-3 and SDF-1, by proteolytic actions and reduce immune cell infiltration into the tumour and promote tumour growth." (PMID 35805035, 2022). "Moreover, MMP7, MMP13, and MMP10 were significantly upregulated in metastatic tumour samples compared with nonmetastatic tumour samples." (PMID 31996191, 2020). "Furthermore, to investigate the role of tumor-derived exosomal MMP-13 in tumor growth and metastasis, normoxic and hypoxic exosomes purified from MMP-13 shRNA-treated cells (200 μg/ml) were then injected into the xenograft tumors." (PMID 29515112, 2018). "Thus, MMP13 played a role in collagen metabolism in invasive areas of MMTV-PyMT tumors, but this did not affect tumor progression." (PMID 18698413, 2008). "Whereas some investigators have not found a significant relationship between MMP-13 expression and HNSCC behavior, we found significant MMP-13 expression in highly invasive tumors; this finding suggests that MMP-13 likely plays a role in regulating tumor invasion." (PMID 15291964, 2004).
cancer (256 papers, 2007 to 2026). A tumor composed of atypical neoplastic, often pleomorphic cells that invade other tissues. "In the search for more promising therapies, matrix metalloproteinases have become of significant interest, such as MMP-1, MMP-2, MMP-9, and MMP-13, which have been linked to more aggressive forms of cancer and earlier metastases." (PMID 39063046, 2024). "In patients with early-stage GC, we also observed the diagnostic ability of serum EFNA1 combined with MMP13 to distinguish cancer patients from normal controls (AUC 0.865, sensitivity 48.5%, specificity 90.2%) (Supplementary excel)." (PMID 38987376, 2024). "Elevated MMP-13 in various cancers is linked to increased invasiveness, metastasis and poor prognosis." (PMID 38067138, 2023). "Genes with known implications in cancer, such as MMP-13, KRT84, OLFM4, GJA1, AMOT and ADAMTS1, were strongly linked to DSG3 overexpression." (PMID 38067138, 2023). "MMP13, an important gene in OA development, is also implicated to play a role in the metastasis of cancer, and, here, the family of ETS transcription factors is also involved in regulation of MMP13 expression." (PMID 32937960, 2020). "The hsa-miR-375 is known to target MMP13, which is associated to increased metastatic behavior and cancer aggressiveness." (PMID 31469874, 2019). "In recent years, there are contradictory results between the -77A/G polymorphisms in the MMP-13 and various types of cancer risk." (PMID 30889876, 2019). "As a consequence, we found cancer stem cell-associated proteins, such as mmp2, mmp9, mmp13, mmp14, paxillin, Ras, src and c-myc, as well as genes expressed in the immune system, such as C5, C9, and HMGB1." (PMID 31832023, 2019). "The excessive expression of MMP13 has been demonstrated to associate with poor survival in various malignant tumors." (PMID 30889876, 2019). "According to the past studies, MMP19, ADAMTS1and MMP13 genes are closely associated with the metastasis and development of malignant tumors." (PMID 27227769, 2016). "Nevertheless, to ensure the diagnostic value of MMP-13 IRS in predicting cancer behaviour at this stage long-term follow-up studies are necessary." (PMID 27716617, 2016). "MMP‐13 expression in these human cancers was associated with cancer progression including cancer cell invasion and metastasis, diagnosis or poor outcome." (PMID 26817521, 2016). "Using a combination of loss- and gain-of-function approaches, we find that MMP13 is the cause of RKIP-mediated inhibition of local cancer invasion." (PMID 26308852, 2015). "Pathological states associated to MMP13 upregulation are different type of cancers, osteoarthritis, and rheumatoid arthritis." (PMID 24658133, 2014). "An overwhelming number of these downregulated gene sets, including those containing MMP-12 and MMP-13 (lower left) are associated with cancer." (PMID 22815700, 2012). "We found that most of the Mmp13 mRNA expressing cells in the MMTV-PyMT tumors are carcinoma-associated myofibroblasts." (PMID 18698413, 2008). "The heightened expression of MMP-13 observed in diverse tumor types indicates its potentially strong association with cancer progression, metastasis, and unfavorable prognosis across several cancers." (PMID 41179937, 2025). "Interestingly, the MUC16 oncogene, which mediates proliferation and migration, and MMP13, implicated in invasion, metastasis, and angiogenesis, show higher mutation rates in LoY tumors of specific cancer types, such as renal papillary cell carcinoma." (PMID 39594721, 2024). "Furthermore, MMP-13 overexpression is associated with poor prognosis, lymph node metastasis, and a shorter overall survival rate in cancer patients." (PMID 37936192, 2023). "Also, MMP13 regulation was demonstrated to be the cause of RKIP‐mediated inhibition of local cancer invasion." (PMID 31304688, 2019).
cancer (continued). "MMP-13, a member of a zinc-dependent proteolytic enzyme family, has been associated with cancer progression and poor prognosis, such as head and neck, lung, and colorectal cancers." (PMID 29510576, 2018). "Interestingly, three of these genes, MMP19, ADAMTS1, and MMP13, have been previously implicated in the regulation of angiogenesis, extra-cellular matrix, cell adhesion, and cancer progression." (PMID 27227769, 2016). "Considering rs2252070 G-to-A change could impact MMP13 promoter activity in cancer cells, we investigated whether there is an allele-specific effect of rs2252070 SNP on MMP13 expression in esophagus tissue specimens." (PMID 27245877, 2016). "In addition to this data, an increase in the presence of MMP-13 is associated with malignant tumors, and the transformation of benign tumors to malignant." (PMID 25664615, 2015). "However, MMP13 was also detected in the cytoplasm of cancer cells and its high immunoexpression was also associated with poor outcome." (PMID 24229053, 2013). "MMPs have been associated with cancer cell invasion and metastasis, including MMP13." (PMID 23185634, 2012). "Furthermore, we have identified three genes implicated in cancer metastasis – MMP13, ST6GAL2, and ENPP1, which pazopanib has demonstrated to downregulate in our study and could act as drug-response biomarkers or a druggable target with regards to the latter." (PMID 35365682, 2022). "In addition, it has been reported that S100A4 may support MMP-9 and MMP-13 gene expression, and also that it may enhance the activity of some MMPs, causing higher cell dissociation and cancer metastasis." (PMID 30060564, 2018). "Considering the importance of MMP13 in cancer development, we selected 4 haplotype-tagging SNPs (htSNP) across the whole MMP13 locus and conducted three large independent hospital-based case-control studies to investigate the association between MMP13 genotypes and ESCC risk." (PMID 27245877, 2016). "Thus, a dual targeting of uPA and MMP-13 might be a possible future strategy in designing therapies aimed at tissue repair or other pathological processes, such as cancer invasion, where proteolytic degradation is a hallmark." (PMID 21326869, 2011). "MMP13, one of the intestinal collagenases involved in cancer cell invasion, has been demonstrated to participate in the migration and metastasis of HCC via TGF-beta pathway." (PMID 39866228, 2025). "In particular, TRPV6, ASIC2, MMP13, and FOXH1 are well known to be implicated in cancer development." (PMID 38457049, 2024). "MMP13 degrades collagen and other matrix components, which is crucial for the invasive potential of cancer cells." (PMID 38707175, 2024). "Recent studies have found that MMP13 (Matrix Metallopeptidase 13) and MUC16 (Mucin 16) are significantly more frequently mutated in LoY across various cancer types." (PMID 39594721, 2024). "EFNA1 and MMP13, as secreted proteins, are overexpressed in many cancers, but their expression in normal tissues is very low or undetectable, suggesting their potential as serum diagnostic markers." (PMID 38987376, 2024). "In this study, the secretion of several proteases including cathepsin-B, MMP-1 and MMP-13 by cancer cells was shown to be significantly increased in response to the presence of galectin-3." (PMID 37055381, 2023). "A significant correlation was found between MMP13 and immune-related molecules in pan-cancer, including chemokine, immunostimulator, MHC and receptor." (PMID 38066539, 2023). "MMP-13 also is critical in pathophysiological conditions such as inflammation, atherosclerosis, RA, and cancer." (PMID 37936192, 2023). "MMP13 is a matrix metalloproteinase that remodels the extracellular matrix and promotes cancer cell invasiveness." (PMID 37758759, 2023). "Overall, the expression, secretion and activation of MMP-13 in cancer is regulated at multiple levels and by many molecules, including cytokines, growth factors and proteases." (PMID 35805035, 2022).